CD86 (CD86 molecule)
Diseases named in the same sentence as CD86 in open-access papers (continued):
Sharing a sentence is not in itself a finding about the gene and the disease.
lymphoma (19 papers, 2010 to 2025). A malignant (clonal) proliferation of B- lymphocytes or T- lymphocytes which involves the lymph nodes, bone marrow and/or extranodal sites. "Another study in diffuse large B cell lymphoma revealed that SUV39H1 upregulated CD86+ and CD163+ tumor–associated macrophages, suggesting a mechanism for lymphoma progression." (PMID 40059829, 2025). "For this purpose, Rag2– γc– mice (n = 22) were intravenously injected with CD19/CD80/CD86-positive Raji lymphoma cells and treated with CAR (2nd Gen) T cells, corresponding to the Kymriah product (Novartis)." (PMID 38340727, 2024). "present an “AND” switch CAR T cell construct that fully activates only when it binds to CD19 and CD80/CD86 found on lymphoma cells." (PMID 38340727, 2024). "In the same study, using a co-culture system, the authors showed that A20 lymphoma cells can internalize CD86 expressed on APCs via CTLA-4." (PMID 35071240, 2021). "Importantly, TIS lymphomas which were used to prime T-cells in vivo exhibited much higher expression of the costimulatory molecule CD86 if they were CD115high." (PMID 40159497, 2025). "IRF4 has been known to regulate the expression of costimulatory molecules (CD80/CD86) and MHC-class-II-dependent antigen presentation in multiple immune cell types, including dendritic cells, CD226+ macrophages, and lymphoma B cells." (PMID 40585371, 2025). "Expression levels of B7-1 (CD80) and B7-2 (CD86), ligands for the activation receptor CD28 and inhibitory receptor CTLA-4 (CD152) on T cells, vary between different models and subtypes of lymphoma." (PMID 25941795, 2015). "Given that previous studies have documented the release of DAMPs capable of driving CD86 expression on BMDC in vitro 34, as well as antigen-agnostic activation of DCs after BH in mouse lymphoma 12, we had expected a similar global activation of cDCs independent from the acquisition of tumor antigen." (PMID 38389838, 2024). "The role of CD80/CD86 is not yet fully clear in lymphoma, but their expression has been noted on tumor cells and/or on cells from the TME." (PMID 35071240, 2021). "Previous studies indicated that early lymphomagenesis in lymphomas is a process related to CD4 + T cells stimulated by H. pylori antigens, and the proliferation of B-cell gastric lymphoma is dependent on CD40-mediated signaling, Th2 activities, co-stimulatory CD80, and CD86." (PMID 34980267, 2022). "Up-regulation of CD80 and CD86 may enhance a T cell response to CLL and lymphoma." (PMID 22084681, 2010). "CD80 and/or CD86 are expressed on the surface of these B cells from most DLBCL patients, although we could not differentiate between lymphoma and other B cells." (PMID 38340727, 2024).
pancreatic cancer (18 papers, 2015 to 2025). "Increased MMP28 expression, elevated CD163 + TAMs, and reduced CD86 + TAMs were significantly correlated with the pancreatic cancer site (P < 0.05)." (PMID 39972459, 2025). "The pancreatic cancer cell lines tested showed high levels of CD86 expression, but low levels of B7-H3 and CD155 expression." (PMID 38893085, 2024). "A large number of CD206 and CD163 positive macrophages, more than CD80 and CD86, were observed in the WT pancreatic tumor and in the corresponding liver metastasis sections, suggesting the relevant presence of M2 macrophages." (PMID 34681678, 2021). "Polyamine blockade therapy significantly increased overall survival of pancreatic tumor-bearing mice, along with macrophage presence (F4/80) and significantly increased T-cell co-stimulatory marker (CD86) in the tumor microenvironment." (PMID 34945011, 2021). "Additionally, comprehensive analysis of pathological staining revealed that anti-CD47 nanobody therapy more effectively reduced the infiltration of F4/80+CD163+ TAMs and increased the infiltration of F4/80+CD86+ TAMs in pancreatic cancer with CCT6A knockdown." (PMID 40374617, 2025). "It was suggested that downregulation of CD86 helps cancer cells to escape from the immune attack; however, its higher expression in malignant cells compared to corresponding control cells was observed in some malignancies, such as pancreatic carcinoma and FL." (PMID 33562532, 2021). "In pancreatic cancer, for example, VISTA appears to be predominantly expressed on CD86+ macrophages, and the expression of inhibitory immune checkpoint genes (VISTA and others combined) was associated with shorter survival." (PMID 35205752, 2022). "Increased CD86 expression were also observed with the TCM from another pancreatic cancer cell line MiaPaCa (data not shown)." (PMID 35692755, 2022). "Immunohistochemical staining of 36 randomly selected pancreatic cancer clinical samples revealed a positive correlation between MMP28 and CD163 (P < 0.05), but a negative correlation between MMP28 and CD86 (P < 0.001), suggesting a close association between MMP28 and CD163 + TAM infiltration." (PMID 39972459, 2025). "Specifically, invasive Tregs in pancreatic cancer can bind to CD80/CD86 on the surface of dendritic cells via surface CTLA-4 to inhibit the function of dendritic cells in tissues, which, in turn, affects the function of cytotoxic CD8+ T cells to suppress immune responses in pancreatic cancer." (PMID 30477520, 2018). "Additionally, gemcitabine treatment in pancreas cancer patients showed no significant changes in proportions of T and B-cells including CD86 and CD80 APCs or CD4+, CD25+ T-cells." (PMID 25889536, 2015). "Subsequent qRT-PCR analysis of 68 pancreatic cancer and adjacent noncancerous tissues samples confirmed elevated MMP28 and CD163 mRNA levels, whereas CD86 mRNA expression was lower in cancer tissues than in noncancerous controls." (PMID 39972459, 2025).
hepatocellular carcinoma (17 papers, 2008 to 2025). A malignant tumor that arises from hepatocytes. "AJCC stage, preoperative hepatitis, and the expression levels of PD-L1 and CD86 in cancer tissues were independent risk factors affecting survival of patients after radical hepatoma surgery." (PMID 37306737, 2023). "The ISX expression strike enhanced the levels of tryptophan catabolic enzymes, indoleamine 2,3-dioxygenase 1 (IDO1), tryptophan 2,3-dioxygenase, and immune checkpoints regulators PD-L1 and B2-7 (CD86) in hepatocellular carcinoma cells." (PMID 41417109, 2025). "In hepatocellular cancer, patients with high expression of PD-L1 or low expression of CD86 had a poor prognosis." (PMID 39329753, 2024). "Herein, the correlation between the expression of tumor-associated macrophages CD86, CD206, and PD-L1 in hepatocellular carcinoma and clinicopathology was analyzed, and their clinical application value in the prognosis assessment of patients was highlighted." (PMID 37306737, 2023). "In addition, to understand the effect of Ansofaxine hydrochloride on the immune microenvironment of hepatocellular carcinoma, we used CD86 and CD206 to stain, suggesting that M1 macrophages increased while M2 macrophages decreased." (PMID 40809022, 2025). "Moreover, hepatocellular carcinoma-associated CD169+ monocytes/macrophages showed elevated expression of HLA-DR and CD86, similar to the pattern we observed in CD169+ monocytes." (PMID 34394090, 2021). "In addition, a number of hepatocellular carcinoma cell lines were shown to respond to IFN-α by inducing CD86 expression." (PMID 18588665, 2008). "Herein, the expression of PD-L1, CD86, and CD206 in hepatocellular carcinoma tissues was investigated, and the application value of PD-L1, CD86, and CD206 in prognosis assessment of hepatocellular carcinoma was revealed." (PMID 37306737, 2023). "The expressions of PD-L1, CD86, and CD206 in hepatocellular carcinoma cells were lower than those in the adjacent microenvironment." (PMID 37306737, 2023). "In other types of cancers, such as hepatocellular carcinoma (HCC), TAMs express either CD86+ (M1 subtype) or CD206+ (M2 subtype)." (PMID 34063667, 2021). "We have reported that the supernatant from human hepatocellular carcinoma (HCC) cells induced functional impairment of DCs as demonstrated by the downregulation of MHC class I and class II, CD80, CD86, and CD83 molecules." (PMID 20182533, 2009).
malaria (16 papers, 2006 to 2025). Malaria is a serious and sometimes fatal disease caused by a parasite that commonly infects a certain type of mosquito which feeds on humans. "Circulating pDC in P. falciparum infected Fulani, an ethnic group less susceptible to symptomatic malaria, on the contrary, display a mature phenotype with upregulated CD86 and HLA-DR expression and strong TLR9 responsiveness." (PMID 28572564, 2017). "In agreement with this, a Malian study of two ethnic groups with differing susceptibility to symptomatic malaria shows in P. falciparum infected malaria-susceptible Dogon, pDC downregulate HLA-DR expression, lack upregulation of CD86 and show impaired responsiveness to TLR9 stimulation." (PMID 28572564, 2017). "The percentage of macrophages expressing HLA-DR and CD86 in the different malaria groups was significantly lower, suggesting ineffective or incomplete activation of the circulating macrophages compared to controls." (PMID 37060041, 2023). "DCs from malaria infected children of the Dogon community expressed lower levels of HLA-DR and CD86 on their DCs, while the frequency of BDCA-2+ pDCs and BDCA-3+ cDC1 increased compared to uninfected counterparts." (PMID 32793231, 2020). "Taken together, our findings show that during an acute malaria episode caused by natural P falciparum infection, CD16+ DC maturation appears impaired with reduced HLA-DR and CD86 but stable CD16 expression." (PMID 30239833, 2019). "Evaluation of pDC maturation in malaria has been limited to the assessment of surface CD86 and HLA-DR." (PMID 28572564, 2017). "In a recent study of P. falciparum malaria infection in malaria‐naïve volunteers, monocyte HLA‐DR and CD86 expressions were increased at the time when parasitaemia was detected on thick blood film, prior to drug treatment." (PMID 27027867, 2016). "Mean expression of TLR‐2 and TLR‐4 was significantly lower in children with acute CM and SMA compared with healthy controls, while HLA‐DR and CD86 expression was significantly lower in all three malaria groups." (PMID 27027867, 2016). "In contrast, expression of CD86 increased significantly in convalescence in all malaria groups and the expression was similar to those observed in healthy controls." (PMID 27027867, 2016). "Our finding of low expression of integrins, TLRs and activation markers HLA‐DR and CD86, on monocytes during acute malaria, is indicative of a contrasting immunosuppressive effect." (PMID 27027867, 2016). "It has been found that blocking the CD80/CD86 signaling pathway disrupts the Th1/Th2 balance in the Plasmodium chabaudi AS malaria model." (PMID 22348301, 2012). "In pregnancy-associated malaria, iRBCs preferentially accumulate in the placenta leading to higher parasite exposure of placental compared to peripheral blood monocytes, and CD80 and CD86 expression was higher in placental compared to peripheral monocytes." (PMID 19680449, 2009). "Accumulation of malaria pigment in placenta was associated with a partial maturation of cord blood myeloid and plasmacytoid DC, as reflected by an up-regulated expression of the major histocompatibility complex class II molecules, but not CD86 molecules." (PMID 19889240, 2009). "During induced malaria after P falciparum sporozoite infection, CD16+ DCs increase HLA-DR and CD86 expression." (PMID 30239833, 2019). "During induced blood-stage malaria, we observed maturation and activation of CD16+ DCs with increased HLA-DR (P < .0001) and CD86 (P = .0002) expression and reduced CD16/FcγRIII expression (P = .003)." (PMID 30239833, 2019). "Children with uncomplicated malaria show reduced human leukocyte antigen (HLA)-DR expression on CD16+ DCs, yet expression of costimulatory molecule CD86 is increased compared with age-matched uninfected controls." (PMID 30239833, 2019).
malaria (continued). "Altered DCs and monocytes, and reduced frequency and low expression of the CD86 and CD80 activation markers, are observed in malaria-infected pregnant women, suggesting DC migration to lymphoid organs." (PMID 28049536, 2017). "We also observed that malaria-exposed individuals had higher frequencies of CD80+ raMBC and CD80+ aaMBC than the non-exposed individuals but only raMBC had higher proportions of CD86+ cells in the exposed group." (PMID 28878766, 2017). "We conducted this study to explore expression of CD11a, CD11b, CD11c, CD18, HLA‐DR, CD86, TLR‐2 and TLR‐4 and production of TNF‐α and IL‐6 by monocytes in Malawian children presenting with different clinical forms of malaria." (PMID 27027867, 2016). "Hemozoin, the malaria pigment, may induce DC activation and maturation via the expression of CD80, CD86 and chemokine receptors CXCR4, promoting their migration to lymphoid organs." (PMID 28049536, 2017). "In clinical malaria, circulating pDC showed a similarly immature phenotype lacking upregulation of CD86 or HLA-DR and significantly reduced CD123 expression during acute disease compared to convalescence." (PMID 28572564, 2017). "DCs incubated with RBCs or pRBCs did not, however, increase expression of MHC class II, CD40, CD80 and CD86, indicating that malaria parasites do not induce DC activation directly." (PMID 16611373, 2006). "The key issue in increasing vaccine efficacy may be enhancing the expression of CD86/MHC II on antigen-presenting cells before vaccination, although whether enhancing CD86/MHC II expression can totally reverse malaria-induced immune inhibition remains to be tested." (PMID 39847577, 2025). "Malaria-exposed women had increased frequencies of CD80+ active and raMBCs and CD86+ resting atypical and classical MBC compared to non-exposed." (PMID 28878766, 2017).
ovarian carcinoma (15 papers, 2014 to 2024). A malignant neoplasm originating from the surface ovarian epithelium. "CX3CR1 was dim correlated with immunostimulators in epithelial ovarian cancer, such as CD86 (R = 0.49, P < 2.2e−16) was the most closely related to CX3CR1." (PMID 38241595, 2024). "In ovarian cancer, many studies have reported CD86 and CD206 as markers of M1 and M2 macrophage expression." (PMID 39478854, 2024). "ACOD1-/- MSLN-CAR-iMACs expressed more pro-inflammatory marker proteins (CD80 and CD86) after being co-cultured with HO-8910 ovarian cancer cells for 24 h." (PMID 37723178, 2023). "We obtained a result that GPC3 on mouse ovarian cancer cells induces CD86 expression on mouse intraperitoneal macrophages." (PMID 24992906, 2014). "In addition, as a result of F4/80+CD86+ macrophage increase in GPC3-expressing mouse ovarian cancer, we analyzed the effect of GPC3 on CD86 expression in mouse intraperitoneal macrophages." (PMID 24992906, 2014). "The results obtained show that ovarian cancer type II lysates induce differentiation of monocytes into macrophage-like cells with a CD1a+/HLA-DR+/CD83− phenotype and significantly higher CD86/HLA-DR expression." (PMID 28589429, 2017). "A chimeric virus of HAdV5 with the human adenovirus serotype 3 fiber knob (Ad5/3) increases gene uptake in dendritic cells, ovarian cancer, and malignant glioma cells via binding to CD80 and CD86." (PMID 25933160, 2015). "The activation of DCs (CD86 +, CD80+, CD83+, HLA-DR+), CTLs (CD3+CD8+) and NKT (CD3+CD56+) cells were all increased in 6B11-OCIK of the three patients during in vitro culture and showed good killing effect on ovarian cancer cells." (PMID 34408750, 2021). "Of note, the ratio of CD163+/CD206+ TAMs to ovarian cancer cells was increased in omental metastatic tumors (p = 0.0234), and the ratio of CD86+ TAMs to ovarian cancer cells was not (p = 0.3777), indicating that the metastatic microenvironment skews CD163+/CD206+ TAM polarization." (PMID 39198883, 2024). "IFN-γ recovers the M1-phenotype through the increased expression of CD86, enhancement of the infiltration of cytotoxic T cells, and the transformation of an immunosuppressive phenotype into an immunostimulatory phenotype in IFN-γ-treated ascites of ovarian cancer." (PMID 37342343, 2023).
psoriasis (15 papers, 2010 to 2025). An autoimmune condition characterized by red, well-delineated plaques with silvery scales that are usually on the extensor surfaces and scalp. "The presence of CD86+ CD14+ CD16+ cells in psoriasis lesions is linked to increased keratinocyte proliferation." (PMID 38399624, 2024). "Within cDC panels, one trait was linked with increased psoriasis risk: CD86+ plasmacytoid DC AC (IVW: OR 1.0007, 95% CI 1.0000–1.0014; p = 3.902391e−02)." (PMID 38558803, 2024). "Given that an increased number of circulating monocytes correlates with psoriasis severity, recent research has found that elevated CD86 expression on intermediate monocytes is associated with psoriasis severity." (PMID 38399624, 2024). "Analysis of cell surface markers expression on B cells (i.e., CD40, CD44, CD80, CD86,CD11b, and HLA-DR) is the key to understand their pathogenic role in psoriasis." (PMID 27532281, 2016). "Evaluation of the pathogenic psoriasis molecular signature demonstrated that clinical relapse may involve compensatory T-cell activation pathways in the presence of CD28-CD80/CD86 blockade." (PMID 34643650, 2021). "As a result, immunostimulatory genes showed higher expression levels within psoriasis than normal tissues, such as CD86, CD48, TNFRSF4, TNFRSF25, ICOS, and CXCR4." (PMID 36685512, 2022). "CD86 contributes to the formation of the immunological synapse between DCs and T-cells, which is critical in the development of psoriasis." (PMID 26819710, 2016). "Upregulation of CD80/CD86 in psoriatic lesions suggests a critical role for the CD28/B7 co-stimulatory system in the pathogenesis of psoriasis." (PMID 20606886, 2010). "Phototherapy and biologic therapy downregulate the expression of CD86, suggesting that CD86 could be used as a marker for monitoring treatment response in psoriasis patients." (PMID 38399624, 2024). "Psoriasis relapse may involve compensatory T-cell activation pathways in the presence of CD28-CD80/CD86 blockade with abatacept." (PMID 34643650, 2021). "Therefore, our results confirm that CD40, CD44, CD80, and CD86 are likelyimportant in the pathogenesis of psoriasis, especially at the active stage." (PMID 27532281, 2016). "Thus, inhibition of the CD28 and CD80/CD86 interaction is expected to restrict the inflammatory processes of psoriasis." (PMID 20606886, 2010). "The number of dendritic cells, marked by CD86 and CD80 antibodies and playing a critical role in the local inflammatory response in psoriasis, and CD4+ cells in the dermis was also decreased after TBTDC NP-PDT." (PMID 39109246, 2024). "Although cytokines such as IL-17, IL-23, and IL-1β are mainly involved in the exacerbation of psoriasis, DC–T cell crosstalk through CD80/CD86 also affects psoriasis." (PMID 34421919, 2021). "The findings suggested that the molecular trigger of psoriasis relapse may not completely rely on the CD28-CD80/CD86 costimulation pathway and/or may be dependent on compensatory T-cell activation pathways in the presence of abatacept." (PMID 34643650, 2021). "Thus far, several studies have indicated that DCs contribute to the initiation of psoriasis through antigen-presenting molecules (e.g., major histocompatibility complex [MHC], MHCII, CD86, and CD40), cytokines (e.g., interferon [IFN], IL-1β, IL-23, and IL-6), and chemokine receptors." (PMID 34421919, 2021).